AK2 (adenylate kinase 2)
Diseases named in the same sentence as AK2 in open-access papers (continued):
Sharing a sentence is not in itself a finding about the gene and the disease.
tumor (30 papers, 2014 to 2025). "The restored expression of S704D-LOXL3 in AK2-deficient cells efficiently rescued the resistance of tumor cells to chemotherapy, further validating that LOXL3 acts downstream of AK2." (PMID 37253718, 2023). "The positive expression of AK2 is associated with tumor progression, and poor survival in patients with pulmonary adenocarcinoma." (PMID 31780678, 2019). "Moreover, reconstitution of AK2 in AK2-deficient tumour cells retards both cell proliferation and tumourigenesis." (PMID 24548998, 2014). "AK2 deficiency enhances cell proliferation and induces tumour formation in a xenograft assay." (PMID 24548998, 2014). "AK2‐K28la inhibits the activity of its phosphokinase, leading to energy metabolism disorders, ATP accumulation and tumour cell proliferation." (PMID 40984037, 2025). "Excessive lactate production, a hallmark of tumor cells, induces the proliferation and metastasis of HCC cells by inhibiting adenylate kinase 2 function." (PMID 38067357, 2023). "AK2 knockdown cells have been shown to exert greater tumor suppression in vitro and in xenograft mice." (PMID 36982634, 2023). "AK2 has also been shown to play a tumor-suppressive role; a low expression of AK2 correlates with poor prognosis in patients with HCC." (PMID 36982634, 2023). "To precisely calculate the correlation between AK2, LOXL3-S704 phosphorylation, and DHODH, we stained the tumor tissues of the 60 HCC patients using antibodies against AK2 while pLOXL3-S704 and DHODH were measured previously." (PMID 37253718, 2023). "Immunohistochemical assays confirmed that tumor samples with a strong p-ERK signal manifested weak AK2 staining." (PMID 35585049, 2022). "The expression level of AK2 in tumor metastases tissues was markedly higher than that in adjacent non-tumor tissues and primary lesions (p < 0.001)." (PMID 34630090, 2021). "The results showed that AK2 mRNA levels were substantially elevated in tumor cells and the contents were much higher in A549 and H1299 cells." (PMID 34630090, 2021). "Another study suggests that AK2 deficiency promotes the in vitro proliferation of breast cancer MCF-7 and C33A cells, and induces tumor formation in xenograft trials." (PMID 34630090, 2021). "The AK2 protein level in the tumor specimen of the sh-circ_0075943 experimental group was meaningfully restrained." (PMID 34887922, 2021). "Remarkably, silencing AK2 exerted the greater tumor suppression roles when combined with hydroxychloroquine, an effective autophagy inhibitor, in vitro and in xenografts mouse models." (PMID 31780678, 2019). "Our findings supported the concept that AK2 overexpression was a marker of increased tumor aggressive behavior." (PMID 31780678, 2019). "In terms of clinicopathological correlation analysis, the overexpression of AK2 was significantly correlated with tumor stage (advanced vs early, P < 0.001), lymphatic metastasis (yes vs no, P < 0.001) and histologic subtype (P = 0.007)." (PMID 31780678, 2019). "Analysis of the dissected tumours showed that the inoculation of AK2 knockdown cells into nude mice led to a significant increase of tumourigenesis." (PMID 24548998, 2014). "To address this perspective of AK2 function in detail, we assessed the pathological significance of AK2 function by examining the connection between AK2 dysregulation and cell proliferation in human tumour cells and cancer tissues." (PMID 24548998, 2014). "We, therefore, propose that AK2 is a negative regulator of tumour growth that activates DUSP26 to suppress cell proliferation by FADD in human cancers." (PMID 24548998, 2014). "Reversely, ablation of endogenous AK2 expression significantly promoted tumour growth in the right side of mouse flank with 70% of substantial tumour progression." (PMID 24548998, 2014).
tumor (continued). "Downregulation of AK2 is frequently found in tumour cells and human cancer tissues showing high levels of phospho-FADDSer194." (PMID 24548998, 2014). "For example, lactylation of adenylate kinase 2 (AK2) enhances tumor cell growth and dissemination." (PMID 41152975, 2025). "Lactate accumulation not only acidifies the microenvironment but also induces lactoylation of adenylate kinase 2 (AK2) at lysine 28, impairing its kinase activity and disrupting energy homeostasis, thereby promoting tumor proliferation, invasion, and metastasis." (PMID 39610917, 2024). "Furthermore, the analysis of exosomes involved in neuroblastoma metastasis revealed that AK2 were upregulated in bone-marrow-metastasis-derived exosomes compared to primary tumor-derived exosomes." (PMID 36982634, 2023). "Totally, enhancing the AK2-BRAF interaction in tumor cells, such as inducing energy deprivation, might provide one strategy to combat BRAF dysfunction." (PMID 35585049, 2022). "We next assessed our hypothesis that AK2 negatively regulates the BRAF activity in growing tumor cells." (PMID 35585049, 2022). "More, given that intracellular AMP levels may be a pivotal determinant of drug resistance as well as tumorigenesis, it should be interesting to examine AK2 levels in tumor cells manifesting drug resistance." (PMID 35585049, 2022). "Interestingly, Sorafenib administration led to near-complete tumor regression in HRASTg/−; AK2+/− mice as effectively as in HRASTg/−; AK2+/+ mice." (PMID 35585049, 2022). "Similarly, AK2 mRNA and protein levels in tumor specimens (n = 55) were also distinctly higher than those in normal specimens adjacent to cancer (n = 55)." (PMID 34887922, 2021). "Increasing evidences show that AK2 plays a vital role in tumor development." (PMID 34630090, 2021). "We next used western blot analysis to determine whether AK2 bound to endogenous CDK4 present within cell lysates of tumour cell lines HeLa and MCF-7 by conducting SDS-PAGE followed by transfer of isolated proteins to PVDF membranes." (PMID 34930213, 2021). "However, it is rarely reported that AK2 affects tumor cell migration, and the specific mechanism is still unclear." (PMID 34630090, 2021). "In this regard, the AK2-FADD (Fas-associated protein with death domain) mediated apoptosis pathway was found to be defective in some tumor cells, which may contribute to tumor development by preventing apoptosis." (PMID 32509571, 2020). "Recently, studies have demonstrated that FADD plays a crucial role in cell growth by interacting with the adenylate kinase 2 (AK2)/dual-specificity phosphatase 26 (DUSP26) protein complex and could be associated with tumor cell differentiation." (PMID 27764170, 2016). "Here we show that AK2 negatively regulates tumour cell growth." (PMID 24548998, 2014). "An increase in AK2 in the mitochondria may favour a decrease in translocation and therefore a decrease in apoptosis promoting tumour growth." (PMID 24728830, 2014). "Furthermore, studies have shown that AK2 overexpression may influence the sensitivity of tumor cells to adjuvant therapy." (PMID 39867576, 2024). "Thus, AK2 could play different roles in various neoplastic diseases that is correlated with the tumor tissue origin, extracellular microenvironment and specific mechanisms." (PMID 31780678, 2019). "Further investigations have indicated that lactylation of adenylate kinase 2 (AK2) lysine 28 diminishes enzymatic function, thereby promoting tumor cell proliferation and metastasis." (PMID 38993478, 2024). "Overall, an inverse correlation was noted between tumor purity and the expression levels of IGF2BP3, EMP3, TUBA1C, AK2 and IGFBP2 (average PCC = −0.48)." (PMID 38171932, 2023). "Tumors from HCC patients showed low-AK2 protein expression and increased ERK activation compared to non-tumor tissues and the downregulation of AK2 was also verified by two microarray datasets (TCGA-LIHC and GSE14520)." (PMID 35585049, 2022).
tumor (continued). "Here, we identified AK2 as an AMP-sensing negative regulator of BRAF and delineated the tumor suppressive role of AK2 in liver tumorigenesis of HRASG12V-transgenic (Tg) mice." (PMID 35585049, 2022). "Purified AK2 bound to rhCDK4 with high specificity and affinity and recognised and interacted specifically with endogenous CDK4 within tumour cells." (PMID 34930213, 2021). "It was also shown that Adenylate kinase 2 (AK2) forms a complex with DUSP26 and stimulates the DUSP26 activity, resulting in the dephosphorylation of FADD and the regulation of tumor cell growth." (PMID 27583453, 2016). "Collectively, AK2 appears to be a strategic controller that acts to coordinate both cell proliferation and FADD dephosphorylation in these tumour cells." (PMID 24548998, 2014). "The ability of AK2 to regulate FADD phosphorylation was also observed in Chang liver and Huh-7 tumour cells." (PMID 24548998, 2014). "We confirmed the interaction between endogenous-BRAF and AK2 in BRAF WT-carrying tumor cell lines including NCTC-1469 normal hepatocyte cells." (PMID 35585049, 2022). "As expected, AK2 expression was significantly downregulated in HCC tumor tissues compared to matched non-tumor or normal tissues in the both datasets." (PMID 35585049, 2022). "After we determined that AK2 could bind specifically and with high affinity to rhCDK4, we next tested whether AK2 could also bind to endogenous CDK4 within tumour cells." (PMID 34930213, 2021). "Therefore, it can be inferred that the knockout of AK2 in A549 cells significantly inhibits the EMT process, thereby inhibiting the metastatic activity of A549 cells and reducing the tumor areas that gather in the liver and lungs of mice." (PMID 34630090, 2021). "Moreover, AK2 specifically recognised and interacted with endogenous CDK4 within tumour cells, thus demonstrating that we successfully obtained a specific human scFv for CDK4." (PMID 34930213, 2021). "In view of this, AK2 has great potential for use in clinical diagnosis and prognosis of tumours based on monitoring of CDK4 biomarkers, while also holding promise as an intrabody-based anti-tumour therapy that acts by targeting intracellular CDK4." (PMID 34930213, 2021). "The expression of AK2 was firstly examined by immunohistochemical staining in 345 tumor tissues and 80 adjacent non-tumor counterparts from patients with LAD in our hospital." (PMID 31780678, 2019). "AK2 content in the tumor tissues was markedly higher than that in the adjacent non-tumor tissues (P < 0.001)." (PMID 31780678, 2019). "In the present study, we show that AK2 forms a protein complex with DUSP26 and stimulates the phosphatase activity of DUSP26 resulting in the dephosphorylation of p-FADD and the regulation of tumour cell growth." (PMID 24548998, 2014). "Compared with control cells, ectopic restoration of AK2 in MCF-7 and C33A cells lacking AK2 expression led to near-complete tumour regression." (PMID 24548998, 2014). "While AMPK has an established and well-studied role in cancer, it has not been previously linked with AK2 in this context, and recently investigated functions of AMPK in regulating cell energy metabolism and tumor cell survival are still emerging." (PMID 24666435, 2014). "Furthermore, AK2 is an AMP-sensing negative regulator of BRAF (B-Raf proto-oncogene) in tumorigenesis, and monitors cellular AMP levels linking metabolic status to the tumor." (PMID 36982634, 2023). "Additionally, AK2 is an activator of the dual-specificity protein phosphatase 26 and suppresses cell proliferation through the dephosphorylation of FADD, suggesting that AK2 is a negative regulator of tumor growth." (PMID 36982634, 2023). "Moreover, AK2/BRAF interaction was abrogated by RAS activation in in vitro assay and cell model and in a mouse model of HRASG12V-driven HCC, and AK2 ablation promoted tumor growth and BRAF activity." (PMID 35585049, 2022).
tumor (continued). "Further analyses of AK2 interactions with intracellular components demonstrated that AK2 recognised and interacted specifically with endogenous CDK4 and thus could be useful for detection of CDK4 within tumour cells." (PMID 34930213, 2021). "In addition, the current results show that AK2 can specifically bind to rhCDK4 and endogenous CDK4 in tumour cells, which indicates that AK2, as a single-chain antibody, maintains its unique biological structure and biological activity in this soluble expression and purification system." (PMID 34930213, 2021). "Fourth, tumour cells lacking AK2 exhibit high level of p-FADD and reconstitution of AK2 reverses it." (PMID 24548998, 2014).
cancer (22 papers, 2012 to 2025). A tumor composed of atypical neoplastic, often pleomorphic cells that invade other tissues. "The types of mutations encompass missense and nonsense mutations as well as deletions, resulting in a massive loss of the AK2 protein in patients with cancer." (PMID 35585049, 2022). "We thus demonstrated that 2-oxo-Ado causes growth arrest and apoptosis dependent on ADK, AK2 and the formation of 2-oxo-ATP (triphosphate form) similarly to various modified adenosines, such as 8-Cl-Ado and 2-Cl-Ado, which are potent anti-cancer drugs." (PMID 28747712, 2017). "AK2 deficiency can destroy cellular energy, leading to human diseases such as amyotrophic lateral sclerosis, severe combined immunodeficiency, deafness and cancer, and is embryonic lethal in mice." (PMID 34630090, 2021). "Indeed, the levels of p-FADD were high in 62% of cancers showing low levels of AK2 expression and in 75% of cancers showing DUSP26 deficiency." (PMID 24548998, 2014). "Despite accumulating evidence supporting the role of AK2 in tumorigenesis, a correlation between AK2 and common driver genes in cancers, including MAPK pathway genes, remains poorly understood." (PMID 35585049, 2022). "We crossed AK2+/− mice with the HRASG12V transgenic (Tg) mouse model of HCC, corresponding to the most frequently mutated form of HRAS found in human cancers." (PMID 35585049, 2022). "Consistent with the results observed in the HCC cell lines, p-ERK levels were elevated in the AK2-underexpressing cancer tissues." (PMID 35585049, 2022). "Among all 46 AK2-underexpressing cancer tissue samples, p-ERK levels were high in 32 samples (69.6%) and low in 14 tissue samples (30.4%)." (PMID 35585049, 2022). "Nonetheless, it can also be seen that for some genes, such as AK2 or KTM2C, more than a single-mutation type leads to high predictivity of multiple cancers." (PMID 34385450, 2021). "In our study, we found that knockdown of AK2 significantly increased the cancer cell apoptosis and suppressed the proliferation in A549 and H1299 cells." (PMID 34630090, 2021). "The contents of AK2 were substantially elevated in cancer cells and relatively higher in A549 and H1299 cells among four LAD cell lines." (PMID 31780678, 2019). "Previous studies have demonstrated a biochemical difference of AK2 in lung tumors, but evidence of its role in other types of cancers is limited." (PMID 24666435, 2014). "Cancer-specific alleviation of AK2 expression was observed in 13 samples (93%), including cancers in clinical phase I (four cases), II (six cases) and III (three cases) phases, out of the 14 matched tissue sets and DUSP26 expression was lost in 57% of cancers." (PMID 24548998, 2014). "There is a correlation between poor clinical outcomes and increased tumor development at particular lactylation sites, including K28 on adenylate kinase 2, which may be directly related to promotion of cancer cell proliferation and metastasis." (PMID 39968078, 2025). "The paradox of whether AK2 acts in a cancer-suppressive or cancer-promoting manner has been suggested to differ depending on the cancer cell type and developmental stage and needs to be assessed further." (PMID 36982634, 2023). "Our data also indicate that targeting AK2 could be an attractive option for cancer therapy since it should preferentially target cells that exhibit high demand for energy." (PMID 35945217, 2022). "Thus, the loss of AK2 is possibly involved in the pathogenesis of not only HCC, but other types of cancer." (PMID 35585049, 2022). "It was found that Ak2 gene expression is upregulated in the metastatic pancreatic endocrine neoplasms, indicating the significance of nucleotide metabolic signaling in cancer invasion." (PMID 32509571, 2020). "There are evidence that the AK2 upregulation could be used by cancer cells to support energy supply to biosynthetic processes and cellular growth." (PMID 32509571, 2020). "Inhibition of AK2 expression significantly inhibited the proliferation of cancer cells." (PMID 28210221, 2017).
cancer (continued). "Our results indicate that the metabolic defects introduced by siRNA silencing of metabolic enzymes TKT or AK2 may be compensated by alternative feedback metabolic mechanisms, suggesting that cancer cells may overcome single defective pathways through secondary metabolic network adaptations." (PMID 24666435, 2014). "Studies indicate that AK isoforms (AK1, AK2, AK4, and AK6) have an important role in the regulation of cancer cell metabolism, metabolic signaling, and cell migration and invasion." (PMID 32509571, 2020). "Specifically, we will overview how AK isoforms, localized in mitochondria (AK2 and AK4), and their main communication partners cytosolic AK (AK1 and AK6) are involved in cancer formation and metastasis." (PMID 32509571, 2020). "We first detected LOXL3-S704 phosphorylation, and AK2 and DHODH protein levels, in the cancer and adjacent tissues of these 50 HCC patients, using the indicated antibodies with the first validating their specificity: LOXL3-S704 phosphorylation was significantly upregulated in the human HCC tissue." (PMID 37253718, 2023). "In another study using proteomic analysis of mouse teratocarcinoma cells, it was demonstrated that metastatic cancer cells have increased AK2 levels than have nonmetastatic cancer cells." (PMID 32509571, 2020). "Specifically, AK2 mediates mitochondrial apoptosis through the formation of an AK2–FADD–caspase 10 complex, whereas NOX4-mediated ROS production induces apoptosis in cancer and normal cells upon stimulation, for instance by incubation with TNF-α, glucose, or anti-cancer drugs." (PMID 31399108, 2019).
immunodeficiency (3 papers, 2022 to 2026). Failure of the immune system to protect the body adequately from infection, due to the absence or insufficiency of some component process or substance. "AK2 deficiency can lead to immune dysfunction and increased susceptibility to infections, highlighting its importance in maintaining a healthy immune system." (PMID 41012626, 2025).
infection (3 papers, 2019 to 2024). The state of being infected such as from the introduction of a foreign agent such as serum, vaccine, antigenic substance or organism. "In infection by Brucella abortus, the AK2/STAT3 pathway is important for the intracellular survival of the bacteria." (PMID 39255287, 2024). "The levels of AK2 mRNA and protein were significantly reduced following infection of lentivirus, comparing with the sh-NC group (p < 0.001)." (PMID 31780678, 2019). "Infection of miR-141-3p + AK2 could restrain the apoptosis of BC cells, and infection of miR-141-3p alone could distinctly accelerate cell apoptosis." (PMID 34887922, 2021).
cardiovascular diseases (1 paper, 2023). "Hence, AK2 could serve as a therapeutic target for cardiovascular diseases such as MI." (PMID 37123453, 2023).
hematological disorder (1 paper, 2019). "Reticular dysgenesis is a rare hematological disorder caused by mutations in the adenylate kinase 2 (AK2) gene." (PMID 31727854, 2019).